MIR4283-1 (microRNA 4283-1)
Synonyms: hsa-mir-4283-1
Gene: MicroRNA gene on chromosome 7 (56,955,785 to 56,955,864, reverse strand). Ensembl gene ENSG00000264426.
Homologues: Paralogues in human: MIR4283-2 (100% identical).